PSMA4 (proteasome 20S subunit alpha 4)
Description:
Component of the 20S core proteasome complex involved in the proteolytic degradation of most intracellular proteins. This complex plays numerous essential roles within the cell by associating with different regulatory particles. Associated with two 19S regulatory particles, forms the 26S proteasome and thus participates in the ATP-dependent degradation of ubiquitinated proteins. The 26S proteasome plays a key role in the maintenance of protein homeostasis by removing misfolded or damaged proteins that could impair cellular functions, and by removing proteins whose functions are no longer required. Associated with the PA200 or PA28, the 20S proteasome mediates ubiquitin-independent protein degradation. This type of proteolysis is required in several pathways including spermatogenesis (20S-PA200 complex) or generation of a subset of MHC class I-presented antigenic peptides (20S-PA28 complex).
Synonyms: HC9; PSC9; HsT17706
Tractability: Small molecule: an approved drug acts on it; a structure with a bound ligand is known; a high-quality ligand is known; it belongs to a druggable protein family. PROTAC: ubiquitination databases record sites on it; its protein half-life has been measured; a small molecule that binds it is known.
Gene: Protein-coding gene on chromosome 15 (78,540,089 to 78,552,417, forward strand). Ensembl gene ENSG00000041357.
Subcellular location: Cytoplasm; Nucleus
Subcellular location (Human Protein Atlas): Cytosol; Nucleoplasm; Connecting piece; Flagellar centriole; Mid piece; Vesicles
Pathways (Reactome):
Immune System: AMPK-induced ERAD and lysosome mediated degradation of PD-L1(CD274); Activation of NF-kappaB in B cells; Antigen processing: Ub, ATP-independent proteasomal degradation; Antigen processing: Ubiquitination & Proteasome degradation; CLEC7A (Dectin-1) signaling; Cross-presentation of soluble exogenous antigens (endosomes); Dectin-1 mediated noncanonical NF-kB signaling; Downstream TCR signaling; ER-Phagosome pathway; FCERI mediated NF-kB activation; GSK3B-mediated proteasomal degradation of PD-L1(CD274); Interleukin-1 signaling; NIK-->noncanonical NF-kB signaling; SPOP-mediated proteasomal degradation of PD-L1(CD274); TNFR2 non-canonical NF-kB pathway
Cell Cycle: APC/C:Cdc20 mediated degradation of Securin; APC/C:Cdh1 mediated degradation of Cdc20 and other APC/C:Cdh1 targeted proteins in late mitosis/early G1; Autodegradation of Cdh1 by Cdh1:APC/C; Autodegradation of the E3 ubiquitin ligase COP1; Cdc20:Phospho-APC/C mediated degradation of Cyclin A; FBXL7 down-regulates AURKA during mitotic entry and in early mitosis; G2/M Checkpoints; SCF(Skp2)-mediated degradation of p27/p21; SCF-beta-TrCP mediated degradation of Emi1; Separation of Sister Chromatids; The role of GTSE1 in G2/M progression after G2 checkpoint; Ubiquitin-Mediated Degradation of Phosphorylated Cdc25A; Ubiquitin-dependent degradation of Cyclin D
Signal Transduction: Asymmetric localization of PCP proteins; Degradation of AXIN; Degradation of DVL; Degradation of GLI1 by the proteasome; Degradation of GLI2 by the proteasome; Degradation of beta-catenin by the destruction complex; GLI3 is processed to GLI3R by the proteasome; Hedgehog 'on' state; Hedgehog ligand biogenesis; MAPK6/MAPK4 signaling; Negative regulation of NOTCH4 signaling; Regulation of PTEN stability and activity
and 28 more pathways
Gene Ontology:
Molecular function: protein binding; structural constituent of proteasome
Biological process: proteasomal protein catabolic process; proteasome-mediated ubiquitin-dependent protein catabolic process; regulation of proteasomal protein catabolic process; response to oxidative stress; apoptotic process; CD8-positive, alpha-beta T cell differentiation; CD8-positive, alpha-beta T cell homeostasis; cellular response to type I interferon; DNA damage response; DNA repair; flagellated sperm motility; immune system process; meiotic cell cycle; negative regulation of regulatory T cell differentiation; positive regulation of interleukin-2 production; positive regulation of tumor necrosis factor production; positive regulation of type II interferon production; proteasomal ubiquitin-independent protein catabolic process; regulation of G1/S transition of mitotic cell cycle; response to type II interferon; spermatogenesis; T-helper 1 cell differentiation; T-helper 17 cell differentiation; thymic T cell selection; protein catabolic process; and 1 more
Cellular component: cytoplasm; cytosol; extracellular exosome; nucleoplasm; nucleus; proteasome complex; proteasome core complex; proteasome core complex, alpha-subunit complex; P-body; proteasome storage granule; spermatoproteasome complex; synaptic vesicle
Genetic constraint (gnomAD): Loss-of-function variants: 5 observed, 25.72 expected, observed/expected ratio (o/e) 0.19, 90% interval 0.1 to 0.41. The upper end of that interval is the gene's LOEUF score, 0.41, which puts it in group 1 of 6, group 1 being the genes least tolerant of losing a copy. Missense variants: 123 observed, 244.95 expected, observed/expected ratio (o/e) 0.5, 90% interval 0.43 to 0.58. Synonymous variants: 72 observed, 78.68 expected, observed/expected ratio (o/e) 0.92, 90% interval 0.76 to 1.11.
Homologues: Orthologues: chimpanzee PSMA4 (100% identical), guinea pig PSMA4 (99% identical), pig PSMA4 (99% identical), rat Psma4 (99% identical), mouse Psma4 (99% identical), tropical clawed frog psma4 (97% identical), macaque PSMA4 (97% identical), zebrafish psma4 (96% identical), rabbit PSMA4 (90% identical), Drosophila melanogaster Prosalpha3 (71% identical), Caenorhabditis elegans pas-3 (64% identical), Drosophila melanogaster Prosalpha3T (52% identical). Paralogues in human: PSMA8 (37% identical), PSMA7 (36% identical), PSMA2 (34% identical), PSMA6 (33% identical), PSMA5 (32% identical), PSMA1 (30% identical), PSMA3 (28% identical), PSMB7 (19% identical), PSMB10 (18% identical), PSMB5 (18% identical), PSMB11 (17% identical), PSMB8 (17% identical), and 6 more.
Diseases named in the same sentence as PSMA4 in open-access papers:
PSMA4 is named in the same sentence as 47 diseases in open-access papers, as found by Europe PMC text mining. Sharing a sentence is not in itself a finding about the gene and the disease. The quoted sentences say what the papers report.
lung carcinoma (20 papers, 2012 to 2025). "Previous studies have observed an association between the PSMA4 gene region and lung cancer risk, which is in line with our MR and colocalization analysis results." (PMID 39529882, 2024). "The colocalization analysis provides compelling evidence that the genetic variants associated with PSMA4 expression are likely to be in causal pathways related to lung cancer risk." (PMID 39529882, 2024). "Although little is known about their roles in cancer, prominent among those were polymorphisms of PSMA4 that play crucial roles in the responsiveness of lung cancer patients to cisplatin-based chemotherapy." (PMID 34943457, 2021). "Previously CHRNA3/CHRNA5/CHRNB4 locus and nearby gene PSMA4 have been associated with increased risk of lung cancer." (PMID 30543688, 2018). "CHRNA5 is in the nicotinic acetylcholine region that has well-known associations with lung cancer and smoking, while PSMA4 is also associated with lung cancer." (PMID 29486777, 2018). "Polymorphisms in PSMA4 contribute to lung cancer susceptibility, and upregulated PSMA4 in lung cancer plays an important role in regulating cell proliferation and apoptosis." (PMID 27966459, 2017). "Two SNPs (rs1051730 and rs8034191, both with p<1×10−17) with strong LD in the regions of 15q25.1 containing CHRNA3, CHRNA5, and PSMA4 are strongly associated with lung cancer risk among ever smokers." (PMID 25233467, 2014). "PSMA4, which encodes proteasome subunit alpha type-4, was reported as a strong candidate mediator of lung cancer cell growth." (PMID 24303001, 2013). "Thus, the causal relationship between PSMA4 and lung cancer, as well as its subtypes, requires further investigation." (PMID 38834983, 2024). "Notably, SNPs within 100 kb of our top multivariate longevity-associated gene, PSMA4, were associated with decreased incidence of chronic obstructive pulmonary disease and lung cancer and increased the risk for coronary artery disease." (PMID 37076473, 2023). "Moreover, susceptibility to lung cancer has an undeniable relationship with PSMA4 polymorphisms, so an increased level of PSMA4 has a significant role in the regulation of cell proliferation and apoptosis in lung cancer." (PMID 33906413, 2021). "A haplotype-based association analysis found that PSMA4 is a strong candidate mediator of lung cancer cell growth, and may directly affect lung cancer susceptibility through its modulation of cell proliferation and apoptosis." (PMID 34299277, 2021). "Additionally, PSMA4 is involved in cancer cell proliferation, also its polymorphisms have been shown to increase the risk of lung cancer in the Chinese Han population." (PMID 34938740, 2021). "PSMA4 polymorphism has been associated to lung cancer risk in Chinese Han population." (PMID 30704472, 2019). "PheWAS confirmed chromosome 15 SNPs as jointly associated with respiratory traits and lung cancer, regulating IREB2, CHRNA3/5, HYKK, and PSMA4." (PMID 41377765, 2025). "The robust associations observed, coupled with the supportive colocalization signals, highlight the potential of PSMA4 in the development of targeted lung cancer therapies." (PMID 39529882, 2024). "The enhanced understanding of PSMA4’s functional role in lung cancer provided by our study, combined with these previous findings, offers a strong rationale for exploring its targeting in therapeutic interventions." (PMID 39529882, 2024). "In this study, we found that the expression level of PSMA4 was significantly upregulated in lung cancer by comparative analysis of lung cancer tissues and normal tissues." (PMID 39529882, 2024). "In conclusion, our genome-wide MR and colocalization analyses have successfully identified PSMA4 as a promising therapeutic target for lung cancer." (PMID 39529882, 2024). "The identification of LTB4R, LTBP4, MPI, and TCN2, in conjunction with PSMA4, highlights the intricate heterogeneity of lung cancer and underscores the necessity for tailored therapeutic strategies." (PMID 39529882, 2024).
lung carcinoma (continued). "Compared to normal lung tissues, lung tumors have higher PSMA4 mRNA levels, and downregulation of PSMA4 expression reduces proteasome activity and induces apoptosis in lung cancer cells." (PMID 37035734, 2023). "Experimental studies have shown that PSMA4 mRNA is increased in lung tumor versus normal samples and plays major roles in cell proliferation using data from lung carcinoma cell lines." (PMID 29486777, 2018). "High IREB2 correlated with improved lung cancer prognosis (nonsignificant in LUSC), high PSMA4 expression correlates with poor prognosis in lung cancer overall but demonstrates a favorable association in LUAD patients​." (PMID 41377765, 2025). "PSMA4 plays a direct role in cell proliferation in lung carcinoma cell lines." (PMID 34650983, 2021). "Cross‐validated SNPs rs16969968/rs12914385, cis‐regulatory hubs for COPD–lung cancer pathogenesis, colocalized with ρ‐HESS‐identified regions, mechanistically linking dysregulation of PSMA4, IREB2, CHRNA3, and CHRNA5 to disease etiology." (PMID 41377765, 2025). "Intersection analysis identified core COPD–lung cancer genes (UBA7, ZDHH5, GMPPB, IREB2, PYGB), with emphysema‐specific IREB2 (lung) and PSMA4 (blood)." (PMID 41377765, 2025). "The presence of heterogeneity in the MR analysis for PSMA4, without evidence of directional pleiotropy, suggests that while there may be variation in the effect of genetic instruments, the overall association with lung cancer risk is not biased." (PMID 39529882, 2024). "In lung cancer, PSMA1-2, PSMA4 and PSMA5 were correlated with better prognosis, whereas PSMA6 and PSMA7 predicted worse survival outcomes." (PMID 27966459, 2017). "With our thresholds (p-value = 0.01; fold change = 2; gene rank: 10%, data type: mRNA), none of the datasets revealed statistically significant differences between lung cancer group and normal tissue group for PSMA1 or PSMA4." (PMID 27966459, 2017). "Current evidence therefore highlights IREB2, but not PSMA4, as a candidate driver in COPD–lung cancer transition." (PMID 41377765, 2025).
breast carcinoma (7 papers, 2017 to 2025). "However, mutation events in PSM genes were relatively rare in cancer, which was also observed in the breast cancer validation dataset where only four PSM genes (PSMA4, PSMB7, PSMD3, and PSME4) harbored mutations." (PMID 36123629, 2022). "The results of a recent study showed that mRNA high expression level of PSMA4 in multiple cancer types were significantly associated with worse prognostic in breast cancer, gastric cancer and HER2-negative gastric cancer; whereas they were correlated with better prognostic in lung adenocarcinoma." (PMID 30704472, 2019). "High-expressed PSMA family genes (e.g., PSMA2, PSMA3, PSMA4, PSMA6, and PSMA7) in breast cancer tissues are reported to be linked to a poor OS of the cancer, but higher levels of PSMA5 and PSMA8 are indicative of better clinical outcomes." (PMID 41141246, 2025). "Compared with normal tissues, PSMA4 was expressed at a much higher level in tumors, demonstrated by 36 analyses involving nine kinds of carcinomas, but six studies showed a reduced expression level of PSMA4 in breast cancer, leukemia, lymphoma and two other cancers." (PMID 27966459, 2017). "PSMA2, PSMA3, PSMA4, PSMA6, and PSMA7 showed high expression levels, which were correlated with poor survival of breast cancer patients." (PMID 36424389, 2022). "Furthermore, PSMA2, PSMA3, PSMA4, PSMA6, and PSMA7 showed high expression levels, which were correlated with poor survival of breast cancer patients." (PMID 34943457, 2021).
COVID-19 (5 papers, 2021 to 2024). A disease caused by infection with severe acute respiratory syndrome coronavirus 2. "Fifteen proteasomal proteins showed an increase in serum levels of COVID-19 patients, most notably PSMA7, PSME1, PSMB3, PSMA4 and PSMA5, whereas PSMD2 was the only one with decreased levels." (PMID 37739942, 2023). "Regarding the expression of 20S subunits in the α- and β-ring the mRNA expression of PSMA4, PSMA5, PSMB2, PSMB9, PSMB10 significantly increased in COVID-19 patients (COV) when compared to healthy control (HC)." (PMID 35327634, 2022). "We observed PSMA4 and PSMA5 overexpression in COVID-19 patients." (PMID 35327634, 2022).
schizophrenia (5 papers, 2018 to 2025). A major psychotic disorder characterized by abnormalities in the perception or expression of reality. "By integrating the results from different prediction approaches, they identified six top candidates that represent promising causal genes for schizophrenia (CNTN4, GATAD2A, GPM6A, MMP16, PSMA4, and TCF4), including the GPM6A gene." (PMID 35328011, 2022). "Among the 41 prioritized causal genes, CNTN4, GATAD2A, GPM6A, MMP16, PSMA4, and TCF4 represent the most promising causal genes for schizophrenia." (PMID 29540662, 2018). "Consistent with the downregulation in the hippocampus, PSMA4 was significantly downregulated in the prefrontal cortex in schizophrenia cases in GSE21138 dataset (P < 0.01)." (PMID 29540662, 2018). "In contrast, PSMA4 was significantly downregulated and CNTN4 showed a trend of downregulation (P = 0.065) in the hippocampus of schizophrenia cases compared with controls." (PMID 29540662, 2018). "Notably, ITIH3, ITIH4, and NT5C2 were selected for depression, while PSMA4 and ITSN1 were identified for schizophrenia." (PMID 38637810, 2024).
lung adenocarcinoma (4 papers, 2013 to 2024). A carcinoma that arises from the lung and is characterized by the presence of malignant glandular epithelial cells. "However, in the replication cohort results, we only observed that PSMA4 has a causal relationship with lung adenocarcinoma." (PMID 38834983, 2024). "Utilizing the YangLab SMR visualization approach has facilitated the illustration of these findings, pointing towards PSMA4 potentially acting as a protective factor against lung adenocarcinoma." (PMID 38834983, 2024). "Indeed, it’s intriguing that while a causal link between PSMA4 and lung adenocarcinoma was not evident in the primary datasets, replication cohorts from eQTLGen and GTEx analyses involving whole blood tissue have suggested a potential causal relationship." (PMID 38834983, 2024). "However, no change in PSMA4 mRNA expression was detected in another study of paired normal lung and lung adenocarcinoma tissue." (PMID 24303001, 2013).
chronic obstructive pulmonary disease (2 papers, 2023 to 2025). A chronic and progressive lung disorder characterized by the loss of elasticity of the bronchial tree and the air sacs, destruction of the air sacs wall, thickening of the bronchial wall, and mucous accumulation in the bronchial tree. "In Early Chronic Obstructive Pulmonary Disease (ECOPD) cohort peripheral blood (n = 104), no significant IREB2/PSMA4 expression differences existed between controls and COPD, regardless of smoking status." (PMID 41377765, 2025).
Sepsis (2 papers, 2024 to 2025). Sepsis is defined as life-threatening organ dysfunction caused by a dysregulated host response to infection. "The MR results for PSMA4 revealed a positive estimate effect, implying a correlation between heightened PSMA4 manifestation and heightened susceptibility to sepsis (OR 1.32, 95% CI 1.20–1.45)." (PMID 38605099, 2024). "The results of this analysis suggested a likely common causal variant in the PSMA4 region between PSMA4 and sepsis (PP.H4 = 0.74)." (PMID 38605099, 2024). "In our study, we found a significant association between PSMA4 and sepsis risk (IEU-B-4980: OR 1.32, p = 1.66E−08; IEU-B-69: OR 1.29, p = 1.38E−05)." (PMID 38605099, 2024). "Notably, PSMA4 demonstrated not only an elevated susceptibility to sepsis (OR 1.32, 95% CI 1.20–1.45, p = 1.66E−08) but also exhibited a robust colocalization with sepsis (PPH4 = 0.74)." (PMID 38605099, 2024). "Consequently, the use of PSMA4 antagonists could represent an innovative approach to mitigating the risk of sepsis." (PMID 38605099, 2024). "In our study, we identified the significant role of PSMA4 in the development of sepsis-related ARDS." (PMID 40116326, 2025). "To summarize, this research offers evidence for the possibility of decreasing the likelihood of sepsis by targeting PSMA4." (PMID 38605099, 2024). "According to the present MR analysis, PSMA4 emerges as a highly encouraging pharmaceutical target for addressing sepsis." (PMID 38605099, 2024). "Our validation of PSMA4 colocalization in the IEU-B-69 further underscores its potential as a therapeutic target for sepsis (PP.H4 = 0.85)." (PMID 38605099, 2024). "Additionally, the filtered cis-eQTL genes were examined across the three mainstream databases, and we finally discovered PSMA4 as a promising druggable target for sepsis-related ARDS treatment." (PMID 40116326, 2025). "Our study has pinpointed PSMA4 as a significant drug target for sepsis through MR analysis." (PMID 38605099, 2024). "Furthermore, powerful evidence for colocalization of PSMA4 with sepsis was detected (PP.H4 = 0.74)." (PMID 38605099, 2024). "Suppression of PSMA4 could potentially decrease the likelihood of sepsis." (PMID 38605099, 2024). "Subsequent drug target analysis confirmed the role of four targets (PSMA4, PDK2, RPS18, and NDUFV3) as druggable genes for sepsis-related ARDS." (PMID 40116326, 2025). "We discovered potential drug targets for sepsis-related ARDS through a comprehensive analysis, among which four druggable targets (PSMA4, PDK2, RPS18, and NDUFV3) should be dialectically treated." (PMID 40116326, 2025).